CD70 (CD70 molecule)
Diseases named in the same sentence as CD70 in open-access papers (continued):
Sharing a sentence is not in itself a finding about the gene and the disease.
lupus (44 papers, 2006 to 2025). "In this study, we identified protein(s) that bind to Gadd45a, assessed their gene and protein expression and their association with CD11a, CD70 mRNA, and lupus disease activity." (PMID 24082908, 2013). "In various autoimmune disorders, including alopecia areata, systemic lupus erythematosus, and multiple sclerosis, elevated CD70 expression has been linked to disease severity and activity, and the overactivation of the CD70‐CD27 signalling pathway exacerbates the autoimmune response." (PMID 40629902, 2025). "In addition, the inhibition of PKCδ, which is a step in the ERK pathway (PKC-ras-raf-MEK-ERK), causes hypomethylation of the CD70 promoter and enhances CD70 expression, resembling that seen in lupus or 5-aza-cytidine treated T cells." (PMID 25988383, 2015). "Thus, methylation status of lupus susceptible genes such as those coding CD70 and CD40L may affect the clinical expression of SLE." (PMID 24000287, 2013). "Defective DNA methylation and CD70 upregulation in CD4+ T cells were seen in lupus‐prone MRL/lpr mice." (PMID 40976999, 2025). "In systemic lupus erythematosus (SLE), the overexpression of CD11a, CD40L, CD70, KIR2DL4, and PRF1 in T lymphocytes is associated with DNA hypomethylation in promoter regions." (PMID 38473997, 2024). "Previous research on systemic lupus erythematosus contended that histone deacetylase was able to mute the expression of CD70 by deacetylating histone in the CD70 gene promoter region and enabling condensed chromatin structure." (PMID 36932256, 2023). "CD70 expression was also increased in the synovium and peripheral blood mononuclear cells (PBMCs) of patients with rheumatoid arthritis, systemic lupus erythematosus (SLE), systemic sclerosis, and Sjogren's syndrome." (PMID 35300124, 2022). "We found that upregulated miR-126 promotes the expression of CD11a and CD70 in lupus CD4+ T cells via inhibiting DNMT1-mediated DNA methylation." (PMID 32308657, 2020). "In this regard, T cells isolated from lupus patients over-express CD70, which correlates with disease activity." (PMID 29717110, 2018). "Studies have investigated the significant role of histone modifications in regulating CD70 expression through affecting the posttranslational marks within the TNFSF7 promoter region in lupus CD4+ T cells." (PMID 28785369, 2017). "It is considered that aberrant histone modifications within the TNFSF7 promoter accompanied with other mechanisms lead the way to the development of lupus through elevating CD70 level in CD4+ T cells." (PMID 27669210, 2016). "In an animal model of lupus, CD70 overexpression on splenic CD4+ cells was observed in 16-week-old MRL/lpr mice with established lupus-like disease but not in their 5-week-old counterparts prior to disease development." (PMID 24000287, 2013). "The aberrant activity of CD4+ T cells in patients with systemic lupus erythematosus (SLE) is associated with DNA hypomethylation of the regulatory regions in CD11a and CD70 genes." (PMID 24082908, 2013). "CD11a and CD70 are both overexpressed in CD4+ T cells of lupus patients, and the degree of overexpression is directly proportional to disease activity." (PMID 21192791, 2010). "In summary, these studies indicate that DNA hypomethylation and deregulated expression of molecules including LFA-1 and CD70 are fundamental for the pathogenesis of both drug-induced and idiopathic human lupus." (PMID 16507100, 2006). "CD70+CD4+ T cells have been reported to increase in many autoimmune diseases, including systemic lupus erythematosus and multiple sclerosis, while CD70+ cancer-associated fibroblasts have been reported to promote proliferation of Tregs and create an environment to evade host immunity." (PMID 39846253, 2025). "Moreover, inhibiting hsa_circ_0012919 corrects the DNA hypomethylation of CD70 and CD11a in lupus CD4+T cells by promoting DNMT1 activity." (PMID 32308657, 2020). "MiR-148a elicited the expression of CD70 and CD11a, similar to lupus patients." (PMID 30808407, 2019).
lupus (continued). "Reduced expression of DNA (cytosine-5)-methyltransferase (DNMT)s and global DNA hypomethylation are observed in both human and murine lupus CD4+ T cells, which are associated with increased expression of autoimmune associated genes such as CD40 ligand (CD40L) and TNFSF7 (CD70) in lupus T cells." (PMID 27070142, 2016). "In addition, the level of DNA damage-inducible 45α (Gadd45α), which is thought to have demethylation capability, is reportedly enhanced in lupus patients and positively correlates with CD11a/CD70 expression." (PMID 25988383, 2015). "In addition to hypomethylation, post-transcriptional modifications on histone protein also play a role in overexpressing CD70 in lupus T cells." (PMID 24000287, 2013). "In addition, lymphocytes from patients with lupus had at least over-expression and promoter demethylation of genes coding for CD11a and CD70, a B cell co-stimulatory molecule." (PMID 16507100, 2006). "Moreover, overexpression of CD27 and its soluble form and surprisingly also a higher expression of CD70 have been documented in several types of autoimmune disorders including systemic lupus erythematosus, rheumatoid arthritis, multiple sclerosis, and psoriasis." (PMID 33996677, 2021). "RFX1 downregulation causes CD11a, CD70 and IL17A overexpression by reducing DNA methylation and increasing H3 acetylation levels in the promoter region of CD11a, CD70 and IL17A in the CD4+ T cells of systemic lupus erythematosus (SLE) patients, which contributes to autoimmune responses." (PMID 31737059, 2019). "Furthermore, lupus flares often occurred after exposure to UV-B irradiation, and positive correlations were found between the expression of Gadd45a and hypomethylation of CD11a/CD70." (PMID 28785369, 2017). "Increased miR-21, miR-148a, and miR-126 in lupus CD4+ T cells reduced the expression of DNMT1 directly or indirectly, leading to DNA hypomethylation and overexpression of autoimmune-associated methylation-sensitive genes such as CD70, lymphocyte function-associated antigen 1 (LFA-1), and CD11a." (PMID 27070142, 2016). "The genes encoding perforin (PRF1), CD11a (ITGAL), CD70 (TNFSF7), CD40L (CD40LG), and the killer cell immunoglobulin-like receptor (KIR) genes are normally suppressed by DNA methylation in CD4+ T cells, but are demethylated and over-expressed by CD4+ T cells from patients with active lupus." (PMID 28239687, 2016). "T-cell autoreactivity in lupus is thought to be due in part to the overexpression of adhesion molecule lymphocyte function-associated antigen 1 (LFA-1, composed of cluster of differentiation (CD) 11a and CD18 subunits), and of CD70 (TNFSF7), which induces B cells to over-produce autoantibodies." (PMID 21192791, 2010). "Abnormal methylation of T cells in SLE patients leads to overexpression of methylation-sensitive autoimmune genes CD70, ITGAL (integrin subunit alpha L) (CD11a), selectin-1, IL-4, and IL-13 in lupus." (PMID 33859701, 2021). "Increased CD70+ CD4+ T lymphocytes were also observed in systemic lupus erythematosus (SLE) and rheumatoid arthritis (RA) patients, further confirming the hypothesis." (PMID 32559178, 2020). "Meanwhile, decrease in methylation level of several immune-related genes, e.g. TGAL (integrin alpha L chain, CD11a), CD40LG, TNFSF7 (CD70), KIR2DL4, and PRF1, can influence their expression in lupus T-cells." (PMID 29803202, 2018). "PBMC from women with inactive and active lupus and inactive and active SS were isolated and stained with fluorochrome conjugated antibodies to CD3, CD4, CD28, CD70, CD40L and the KIR gene family then analyzed by multicolor flow cytometry." (PMID 28620656, 2017). "The PP5 over-expression is consistent with the decreased Dnmt1 levels and increased KIR, perforin, CD40L, CD70, and CD11a expression seen in CD4+CD28+ T cells from lupus patients." (PMID 28239687, 2016).
lupus (continued). "In addition to these linage-specific cytokines and transcription factors, other genes such as HTR1A, LFA-1, CD70, perforin, and CD40L have been found to be demethylated in lupus CD4+ T cells and have been associated with the pathogenesis of SLE." (PMID 25988383, 2015). "Subsequently, hypomethylation of certain genes have been identified as important in lupus T cells, such as ITGAL (CD11a), CD40LG (CD40L), TNFSF7 (CD70), Killer-cell immunoglobulin-like receptor (KIR2DL4), perforin (PRF1), and CD5 in lupus B cells." (PMID 25566322, 2014). "In this work we have determined the transcript expression of five genes that have proved relevant to lupus and we have confirmed previous observations of high expression of three of them: ITGAL, PRF1, and CD70." (PMID 23029299, 2012). "CD4+ T cells from patients with active lupus overexpress LFA-1, perforin, CD70, and CD40L because of demethylation of the same sequences demethylated by a Dnmt inhibitor." (PMID 18560522, 2008). "In addition to type I IFN signature genes, many other hypomethylated genes (such as CD70, ITGAL, IL10, and IL17) have been identified in lupus cells, which contributed to abnormal immune cell activation and inflammation in lupus." (PMID 38153351, 2023). "Moreover, the epigenetic mechanism of lupus suggests that the abnormal DNA hypomethylation of T cells results in the excessive expression of methylation-sensitive autoimmunity-related genes such as CD70, ITGAL, selectin-l, IL-4, and IL-13 in lupus." (PMID 33282947, 2020). "Similarly, our results revealed that in PBMC from SLE patients, several genes including CD70, ITGAL, selectin-l, and IL-13, all of which are hypomethylated and intensify lupus in different ways, are reduced by MSC." (PMID 33282947, 2020). "RFX1 downregulation caused CD11a, CD70, and IL17A overexpression by reducing DNA methylation and increasing H3 acetylation levels in the promoter region of CD11a, CD70, and IL17A in the CD4+ T cells of systemic lupus erythematosus (SLE) patients, which contributed to autoimmune responses." (PMID 30857550, 2019). "CD4+CD28− stress-induced, PP5 overexpressing T cells have decreased ERK and JNK pathway signaling, low Dnmt1 levels, and overexpress methylation sensitive genes including KIR2DL4, CD70 and perforin, similar to the epigenetically altered CD4+CD28+ T cells from patients with active lupus." (PMID 28239687, 2016). "It has been shown that autoimmune responses in SLE may partly be explained by Regulatory factor X-box 1 (RFX1) downregulation, which results in histone H3 hyperacetylation at the promoter region of CD11a and CD70 genein CD4+ T cells of patients with systemic lupus erythematosus (SLE)." (PMID 27669210, 2016). "Global histone H3 and H4 hypoacetylation has been found in lupus CD4+ T cells, and aberrant histone modifications have been observed within the TNFSF7 promoter, leading to CD70 overexpression on T cells, which may contribute to the disease." (PMID 25988383, 2015). "In lupus-prone MRL/lpr mice, defective DNA methylation and CD70 overexpression in CD4+ T cells could be detected." (PMID 27747498, 2015). "In vitro treatment of lupus CD4+ T cells with a histone deacetylase inhibitor was demonstrated to overexpress CD70 in these cells by aberrant histone modifications (increase in H3 and H4 acetylation levels) within the TNFSF7 promotor region." (PMID 24000287, 2013). "Beyond oncology, CD70-targeting AlloCAR70-NKT cells may have utility in T cell-mediated autoimmune diseases, where activated CD70+ T cells contribute to pathogenesis, including multiple sclerosis, inflammatory bowel disease, and lupus." (PMID 40885188, 2025). "In systemic lupus erythematosus (SLE), regulatory factor X 1 (RFX1) was found to be able to recruit HDAC1 to the promoter region of CD70 and deacetylate the histone substrate, resulting in a more condense chromatin structure and a decrease in the expression level of CD70." (PMID 35585975, 2022).
lupus (continued). "In systemic lupus erythematosus (SLE), RFX1 downregulated IL17A, CD70, and CD11a expression by recruiting DNMT1, HDAC1, and SUV39H1 to alter epigenetic modifications in CD4+ T cells from patients with lupus." (PMID 30857550, 2019). "One study found that the overexpression of miR-125 correlates to the reduction of DNMT1 protein expression in lupus CD4+ T cells, and another study reported overexpression of miR-126 in healthy donor CD4+ T cells that led to hypomethylation and overexpression of genes CD11a and CD70." (PMID 25566322, 2014). "As indicated from the results, circ_0012919 reduction enriched the expression of DNMT1, decreased the expressions of CD70 and CD11a, and reversed the DNA hypomethylation of CD11a and CD70 in CD4+ T cells of systemic lupus erythematosus (SLE); however, it was reversible by DNMT1 reduction." (PMID 32665846, 2020). "Increased CD70 expression on T cells was previously detected in patients with rheumatoid arthritis and systemic lupus erythematosus, but it is not studied whether CD70 upregulation on Tfh cells takes place during autoimmune diseases and has a role in broadening B cell responses toward autoantigens." (PMID 28473831, 2017). "In humans, CD4+ T cells of patients with SLE were also shown to overexpress CD70 when compared to healthy subjects, although CD70 expression on CD4+ T cells has not been found to be consistently correlated with lupus disease activity." (PMID 24000287, 2013).
renal cell carcinoma (39 papers, 2006 to 2026). "CD70 also appears in solid tumors such as renal cell carcinoma, nasopharyngeal carcinoma, glioblastoma, melanoma, and carcinomas of the lung, cervix, breast, ovary, and mesothelium." (PMID 40896423, 2025). "The first‐ever durable full remission (lasting more than 3 years) in solid tumours was achieved with an off‐the‐shelf CAR‐T method using CRISPR‐edited T cell therapy (CTX130) that targets CD70 in advanced renal cell carcinoma." (PMID 40685330, 2025). "In CAR-T therapy research for renal cell carcinoma, two clinical trials are exploring different optimization pathways that focus on the CD70 and CAIX targets, respectively." (PMID 40969260, 2025). "CD70 is a surface marker that is aberrantly exhibited in different types of cancer, including renal cell carcinoma." (PMID 40007761, 2024). "In this study, we investigated CD70 as a promising target for renal cell carcinoma (RCC) therapy and developed a potent chimeric antigen receptor T (CAR-T) cells for potential clinical testing." (PMID 38637886, 2024). "CD70 is a biomarker of renal cell carcinoma, non-small cell lung cancer, melanomas, and glioblastoma multiforme." (PMID 37371075, 2023). "Of note, the CD70 overexpressing cancers include diseases in need of better treatment options, including renal cell carcinoma, cervix carcinoma, glioblastoma, and lung carcinoma." (PMID 37093350, 2023). "The three cancer cell lines showed different levels of CD70 expression, with the renal cell carcinoma (RCC) cell line, 786-O, presenting the highest membrane CD70 protein levels, and the lung cancer cell line, NCl-H1975, the lowest CD70 expression." (PMID 37093350, 2023). "Allogeneic CAR-T cells targeting CD70 have shown efficacy in the treatment of renal cell carcinoma and have entered phase I clinical trials." (PMID 37143720, 2023). "NCT05518253 is a single-center, double-arm, open-label phase I trial that evaluates the tolerability and safety of CAR-T cells in patients with CD70-expressing advanced/metastatic solid tumors, including renal cell carcinoma and ovarian and cervical cancer." (PMID 37371075, 2023). "In renal cell carcinoma, tumor infiltrating lymphocytes were found to have an exhausted phenotype, which was driven by CD70 expression." (PMID 34991665, 2022). "Its ligand, CD70, is only transiently expressed on activated T-cells, B-cells, and mature dendritic cells, while its overexpression has been reported in renal cell carcinoma and hematological malignancies." (PMID 34200100, 2021). "Previous studies revealed the aberrant expression of CD70 in several hematological malignancies and solid malignant tumors, including lung cancer, renal cell carcinoma, glioblastoma osteosarcoma, nasopharyngeal carcinoma and ovarian carcinoma." (PMID 35145909, 2021). "CD27-positive TIL are indicated to correlate with activated T-cell response in non-small cell lung cancer and renal cell carcinoma, both of which are known as CD70-expressing tumors." (PMID 35145909, 2021). "In tumour types, such as renal cell carcinoma, hepatocellular carcinoma, and head & neck carcinoma, tissues from both primary and metastatic sites were similarly positive for CD70." (PMID 31652572, 2019). "CD70 positivity was significantly most prevalent in the samples of renal cell carcinoma (79.5%), as compared to all other tumour types (p < 0.0001)." (PMID 31652572, 2019). "In solid tumours, 43% demonstrated CD70 positivity with the highest degree in renal cell carcinoma (79.5%)." (PMID 31652572, 2019). "CD70 expression in more than 50% of the tumour cells was mainly observed in renal cell carcinoma (61.5%, N = 39), gastric carcinoma (50%, N = 6), and adenoid cystic carcinoma (60%, N = 5)." (PMID 31652572, 2019). "Our study demonstrated that 79.5% of all renal cell carcinoma patients (39 in total) were positive for CD70." (PMID 31652572, 2019).